ALDH2 (aldehyde dehydrogenase 2 family member)
Diseases named in the same sentence as ALDH2 in open-access papers (continued):
Sharing a sentence is not in itself a finding about the gene and the disease.
cancer (continued). "This aligned with the previous researches suggesting the involvement of ALDH2 in various cancers and its role in metabolizing substances, including alcohol, which can influence cancers development." (PMID 39132147, 2024). "Upon re-examining of The Cancer Genome Atlas data, we observed a weak but significant correlation between ALDH2 and the IL-17A gene in certain types of cancers." (PMID 38226171, 2024). "From our analysis, we found that the effects of ADH1B and ALDH2 are not limited to cancer onset, but also contribute to cancer prognosis." (PMID 37706329, 2023). "Carriers with the both ADH1B rs1229984 TC/CC and ALDH2 rs671 GA/AA genotypes had a higher risk of cancer than those with the both ADH1B rs1229984 TT and ALDH2 rs671 GA/AA genotypes." (PMID 35670037, 2023). "The strong association between inactive ALDH2 and the risk of UADT cancer with drinking alcohol and cigarette smoking has been reviewed in many publications." (PMID 37409321, 2023). "They reported strong correlations between ALDH2*2/*2 (ALDH2 rs671 AA genotype) and cancers of the oropharynx and esophagus." (PMID 35670037, 2023). "In HNSC, we observe a positive association between ALDH2 expression and the infiltration of monocytes, M1 macrophages, and naïve B cells in HPV-unrelated cancers." (PMID 37476181, 2023). "The mechanisms behind the repressed ALDH2 levels include genetic instability 5-7, enhanced cancer stemness 8, and dysregulated immunity 9-11." (PMID 37476181, 2023). "We found the relationship between ALDH2 expression, and LUAD patient survival time associated with various clinicopathological factors: cancer stage, smoking habit, gender, and treatment strategy." (PMID 36936815, 2023). "Aldehyde dehydrogenase (ALDH2)) and aldehyde dehydrogenases are often highly expressed in cancer stem cells." (PMID 36983764, 2023). "Analysis of the TCGA database showed significantly lower ALDH2 mRNA levels in the bulk tumors compared to the normal samples in 17 different cancers." (PMID 37476181, 2023). "The TISCH database indicates that the ALDH2 levels in macrophages/monocytes are higher than in the cancer cells in all 3 cohorts, suggesting that the ALDH2 levels in the immune cells play a predominant role." (PMID 37476181, 2023). "Stem-cell-related factors, such as SOX2, KLF4, NANOG, OCT4, ALDH1, and ALDH2, have been reported to be vital for maintaining cell self-renewal traits in many types of cancer." (PMID 36674577, 2023). "Using data from the prospective China Kadoorie Biobank (CKB), we investigated the associations of ALDH2‐rs671 and ADH1B‐rs1229984 with total and common site‐specific cancers in 151 000 Chinese adults." (PMID 35048370, 2022). "The strong association between ALDH2*2 mutation and the risk of UADT cancer with alcohol consumption and cigarette smoking has been reviewed in many publications." (PMID 35330099, 2022). "Multiple original studies, reviews and meta-analyses and from Asia also found that the mutation of ALDH2*2 and the deficiency of ALDH2 enzyme activity were commonly implicated in UADT cancers due to the increased DNA damage induced by acetaldehyde cancers." (PMID 35517510, 2022). "In our study, the effects of ALDH2‐rs671 genotype on UADT cancers in different drinking groups were influenced by a potential gene‐environment interaction between alcohol intake and genotype." (PMID 35048370, 2022). "Compared to normal tissues, the expression level of ALDH2 in cancer tissues was significantly reduced." (PMID 35169188, 2022). "In the present study, we found that ALDH2 was downregulated in HNSC cancer tissues compared to normal tissues and that high ALDH2 expression indicated a good prognosis and was associated with lower tumour stage." (PMID 35169188, 2022). "In conclusion, in Chinese men ALDH2‐rs671 G>A and ADH1B‐rs1229984 G>A genotypes were associated with lower risks of overall and IARC alcohol‐related cancers, mainly UADT cancers." (PMID 35048370, 2022).
cancer (continued). "It is also worth noting that a close relationship between the presence of ALDH2 SNPs and many types of cancer has been reported." (PMID 34940794, 2022). "Similar ALDH2‐rs671‐alcohol interactions were observed as in the main analyses after excluding individuals with prior cancer or further adjusting for HBV infection status." (PMID 35048370, 2022). "These methods and information can be applied to ALDH2*2 patients with multiple UADT cancer in the future for personalized medicine." (PMID 35330099, 2022). "Because ALDH2 is closely related to the immune system, it is worth investigating the role of ALDH2 in cancer immunotherapy." (PMID 35169188, 2022). "Epidemiological studies have clearly indicated that ALDH2*2 is associated with increased the susceptibility of synchronous and metachronous UADT cancers and is highly represented in the majority of these cancer patients." (PMID 35330099, 2022). "Joint knockout of the Aldh2 and Fancd2 genes in mice was shown to result in bone marrow failure and elevated cancer development." (PMID 35454946, 2022). "Among them, in addition to those on CCVDs, the mechanisms of ALDH2 involvement in cancer have been widely reported, including digestive system cancer, lung cancer, breast cancer, head and neck cancer." (PMID 35269824, 2022). "This review will therefore focus on studies that have indicated or implicated differences in clinical diagnosis, progression, prognosis and outcome in East Asian UADT cancer patients with regard to the ALDH2 genetic status." (PMID 35330099, 2022). "I encourage the readers, who are more interested in the relationship between the activity of ALDH2 and the metabolism of cancer cells, to read a very good paper entitled ‘ALDH2 and Cancer Therapy’ by Wang and Wu." (PMID 34940794, 2022). "This review summarizes recent publications on the risk and association of ALDH2*2 mutation, alcohol consumption in synchronous, metachronous UADT cancer." (PMID 35330099, 2022). "Although previous studies have shown that significant differences in the ALDH2 genotype lead to different prognoses in cancer patients, its biological roles and prognostic value in HNSC have rarely been characterized." (PMID 35169188, 2022). "Due to its worse prognostic impact, the influence of ALDH2 on cancer progress and prognosis, it also implies the need of knowing the genetic status of the patients and patient education when considering treatment options." (PMID 35330099, 2022). "At the protein level, ALDH2 expression was consistent with the mRNA expression, and the expression of ALDH2 was in plasma in carcinoma and adjacent tissue." (PMID 36144737, 2022). "The dysfunction of ALDH2 has a tight correlation with multiple diseases such as diabetes, cardiovascular disease, osteoporosis, and cancers." (PMID 35096916, 2021). "In our study, we systematically and comprehensively explored the molecular alterations, prognosis, and therapeutic value of ALDH2 in 33 cancer types." (PMID 35096916, 2021). "ALDH2-deficient humans who habitually consume alcohol have a higher cancer rate than humans with functional ALDH2." (PMID 34575850, 2021). "This study advanced the understanding of ALDH2 across cancers, and laid a foundation for the translational medicine developments of ALDH2." (PMID 35096916, 2021). "In this study, we are committed to systematically and comprehensively exploring the molecular alterations, prognosis, and therapeutic value of ALDH2 in 33 cancer types." (PMID 35096916, 2021). "The correlation between ALDH2 expression and the activity of pathways involved in 50 cancer hallmarks was explored to further understand the molecular mechanism of ALDH2 involvement in cancer." (PMID 35096916, 2021). "It was found that ALDH2 was downregulated in most cancer, which was mainly driven by DNA hypermethylation rather than mutation or CNV." (PMID 35096916, 2021).
cancer (continued). "In detail, ALDH9H1, ALDH18A1, ALDH3A2, ALDH1A1, ALDH1B1 and ALDH2 were expressed higher than other ALDH family genes in all cancers." (PMID 34670872, 2021). "In fact, the inhibition of ALDH2 was also shown to exhibit beneficial effect to chemotherapy in other cancer types." (PMID 34026438, 2021). "One is ALDH2 (aldehyde dehydrogenase 2), a stem cell marker that promotes cell proliferation and doxorubicin resistance when overexpressed in cancer cells." (PMID 33671634, 2021). "Based on the PARIS prediction, cancer cell lines that express low levels of ALDH2 become dependent on BRIP1, possibly to balance a harmful increase in genomic instability." (PMID 34454516, 2021). "Bioinformatics enrichment function was found that the changes of ALDH2 participate in cancer mainly through the regulation of immune function." (PMID 34670872, 2021). "In a word, our study demonstrates the important value of ALDH2 in cancer and lays the foundation for translational medicine development of ALDH2." (PMID 35096916, 2021). "Due to the enriched immune-related pathway across cancers, we further assessed the correlation between ALDH2 expression and 24 immune checkpoints expression and 28 immune cells infiltration." (PMID 35096916, 2021). "By assessing the correlation between ALDH2 and cancer pathway activity as well as its clinical value, ALDH2 was found to be a potential biomarker for immunotherapeutic evaluation and prognostic stratification." (PMID 35096916, 2021). "Overall, we suggest that in a cancer context, low ALDH2 expression can be used as a parameter to predict treatment outcome of drugs targeting the FA pathway, which can be potentially developed for clinical use." (PMID 34454516, 2021). "ALDH1 and ALDH2 are also biomarkers of cancer stem cells (CSCs) and related to cancer cells’ proliferation, metastasis, and multidrug resistance (MDR) while the detailed mechanism remains to be elucidated." (PMID 34907179, 2021). "Our research demonstrated the close correlation between the aberrant expression of ALDH2 and the activity of cancer pathways." (PMID 35096916, 2021). "It was proven that aberrant expression and genetic alterations of ALDH2 are widespread in different types of cancer." (PMID 35096916, 2021). "By immunofluorescence staining, myc‐tagged ALDH2 was shown to co‐localize with endogenously expressed PD‐L1 on cancer cell surface." (PMID 34026438, 2021). "Among the genes listed in the COSMIC50 database for cancer, seven blood lifespan cis-eGenes (ALDH2, BCL3, CDKN2A, FES, HIST1H3B, SH2B3, and SMARCA4) were identified (fold enrichment = 1.4, P = 0.22, hypergeometric test)." (PMID 32358504, 2020). "The HER2-specific antibodies studied by us, suppressing the content of ALDH2 mRNA in cancer cells, probably also induce the accumulation of endogenous formaldehyde, which makes an additional contribution to their anticancer properties." (PMID 31700025, 2019). "Alternatively, an understanding of natural ICLs has allowed the development of molecular-targeted drugs, such as alda-1 (ALDH2 agonist) and metformin (aldehyde scavenger), for the prevention of cancer or BMF in patients with FA." (PMID 30873250, 2019). "Most mitochondrial matrix protein-coding genes were significantly upregulated in tumors between the 5 different cancers, which was opposite to the ALDH2 DE." (PMID 29426835, 2018). "Fortunately, the transcriptomic data can provide experimental evidence for ALDH2 activity in cancer patients, which provide additional support for our literature evidence in the next section." (PMID 29552329, 2018). "On the other hand, increasing mitochondria-associated gene expression is commonly observed during carcinogenesis or cancer progression, which was compatible but also opposite to the ALDH2 downregulation in the current study." (PMID 29426835, 2018). "Most TOM complex proteins were upregulated in tumors among the 5 cancer types, which is also opposite to the DE of ALDH2." (PMID 29426835, 2018).
cancer (continued). "Cancer cells rely on detoxification enzymes such as ALDH2 that can neutralise aldehydes and keep a semblance of metabolic equilibrium." (PMID 30088263, 2018). "Several studies have demonstrated the correlation between ALDH2 gene or SOD2 gene polymorphisms and susceptibility to cancer development." (PMID 28841898, 2017). "Lower mRNA expression of VHL, HNF-4α and ALDH2 were found in cancer tissues compared to their corresponding adjacent tissues, and there was a positive correlation between VHL and HNF-4α mRNA and between HNF-4α and ALDH2 mRNA." (PMID 28643803, 2017). "Significantly lower expression of VHL, HNF-4α and ALDH2 were found in cancer tissues than their corresponding adjacent tissues." (PMID 28643803, 2017). "As for this, 114 cases of RCC samples were collected to detect the expression of VHL, HNF-4α and ALDH2 in cancer and adjacent tissues by immunohistochemical assay." (PMID 28643803, 2017). "In the present study, heavy drinkers with ALDH2*2/2*2, ALDH2*1/2*2, and ALDH2*1/2*1 genotypes comprised 3.9%, 25.5%, and 14.7% of the cancer group, and 2.5%, 20.0%, and 0.8% of the control group, respectively." (PMID 21672255, 2011). "The results revealed effect modifications by these polymorphisms for several types of cancer in individuals expected to be rapidly or extensively exposed to acetaldehyde due to the presence of ADH1B and/or ALDH2 gene polymorphisms." (PMID 19667493, 2009). "ALDH2 and CYP2A6 may contribute to cancer risk, underscoring the importance of abstinence from alcohol and smoking in preventive healthcare." (PMID 41680362, 2026). "Additionally, during the development of liver hepatocellular carcinoma, increased autophagy mediated by ALDH2 activation can promote the infiltration of T cells in tumors to limit cancer cell immune escape and suppress tumor growth." (PMID 40968356, 2025). "This substantial reduction in ALDH2 activity in ALDH2*2 carriers compromises aldehyde detoxification, increasing susceptibility to aldehyde-related health risks such as upper aerodigestive tract (UADT) cancer and cardiovascular disease." (PMID 40564981, 2025). "We also compared the RNA expression of ALDH2 in cancerous and peritumoral tissues from seven PC patients who underwent surgery, and the results showed that the RNA expression of ALDH2 was lower in cancer tissues." (PMID 40137171, 2025). "Lastly, we investigated whether ALDH2 expression is functionally correlated with Th17 activity in humans, particularly in a cancer context." (PMID 38226171, 2024). "ALDH2 overexpression potently inhibited cancer cell colony formation and proliferation in vitro." (PMID 38725845, 2024). "In contrast, research suggests that ALDH2 levels, rather than ALDH2 variants, participate in the regulation of carcinogenesis and cancer behaviors through genetic instability 5-7, self-renewal of cancer stem cells 8, and tumor immune microenvironment 9-11." (PMID 37476181, 2023). "An additional reason is ALDH2 level may regulate immunity surveillance, and the effect varies depending on the type of cancer 10,11." (PMID 37476181, 2023). "ob-aT bASCs exhibited an increased ability to stimulate cancer stemness in highly malignant MDA-MB-231 cells by enhancing the gene expression of pluripotency and CSC associated genes such as ALDH1H1, ALDH2, c-MYC, CD34, LGR5, CXCR4, SOX2 and OCT4, fueling further their malignant potential." (PMID 36710348, 2023). "We evaluated ALDH2 gene expression across 24 different types of cancer including LUAD." (PMID 36936815, 2023).
cancer (continued). "Based on this observation, we speculate that dysfunctional variants in Aldehyde Dehydrogenase 2 Family Member (ALDH2) may result in aldehyde-induced BRCA2 haploinsufficiency and increase cancer risk in BRCA2 mutation carriers." (PMID 37943872, 2023). "Confounding may occur in our interpretation of the relationship between ALDH2 levels and overall survival if a patient dies from comorbidity before cancer." (PMID 37476181, 2023). "Understanding the mechanisms underlying ALDH2 downregulation or inactivation in cancers not involving ALDH2 polymorphisms is crucial." (PMID 36831600, 2023). "More implementation is needed to outline a possible role for ALDH2 in cancer." (PMID 36694633, 2023). "This could mean that higher levels of endogenous DNA damage are generated in cultured cell lines than in the HBOC patient body (such as in cancer‐initiating breast epithelium), necessitating the interplay between ALDH2 and HR in cell lines." (PMID 36345163, 2023). "Preceding preclinical studies have demonstrated that the ALDH2*2 allele, which encodes a dominant-negative enzyme variant with reduced activity, can alter cancer cells' biological behaviors and phenotypes in various ways 3,4." (PMID 37476181, 2023). "In both BRCA1 and BRCA2 mutated cohorts, the mean age at cancer diagnosis is not statistically different in cases with ALDH2 AA genotype than those with the GG or GA." (PMID 36345163, 2023). "On the other hand, ALDH2 rs671 was found to be associated with alcohol‐related phenotypes, but not with cancers in the head and neck region in this study." (PMID 35670037, 2023). "Unlike the effects in hematopoietic cells of FA, our current data suggest that there is no impact of the loss of ALDH2 function in cancer initiation and development in breast epithelium of HBOC patients." (PMID 36345163, 2023). "Various researches have found that ALDH2 may play an important part in cancer development and progression." (PMID 36925967, 2023). "Considering the consequences of low ALDH2 expression, leading to AcAH accumulation and compensation by other enzymes, it is plausible to explain how ALDH2 downregulation in tumor tissues contributes to the poor prognosis of cancer patients." (PMID 36831600, 2023). "Therfore, ALDH2 has received extensive attention in cancer and cardiovascular disease." (PMID 36200595, 2023). "However, the reported risks of alcohol‐associated cancers related to ADH1B rs1229984 and ALDH2 rs671 in East Asians are inconsistent, and heterogeneity in distinct studies has been substantial." (PMID 35670037, 2023). "Indeed, ALDH2 dysfunction has been widely reported to correlate with tumor initiation and progression in various cancers." (PMID 36831600, 2023). "In future studies, it may be possible to improve and prevent CRCI by regulating the function of ALDH2 in the brain, which will greatly enhance the QoL of patients with cancer undergoing chemotherapy." (PMID 36200595, 2023). "We genotyped ALDH2 in 103 HBOC patients recruited from multiple cancer centers in Japan." (PMID 36345163, 2023). "Another study concluded that the ALDH2 variant may increase the levels of aldehydes that destabilize BRCA2 protein, accelerating genome instability and cancer initiation." (PMID 36345163, 2023). "We then investigated methylation levels of ALDH2 across 33 different cancer types including LUAD." (PMID 36936815, 2023). "Low ALDH2 expression leads to the accumulation of aldehydic products such as acetaldehyde, 4-HNE, and malondialdehyde (MDA), all of which are associated with high cancer morbidity." (PMID 36936815, 2023). "The ALDH2 expression from TCGA pan-cancer data was analysed." (PMID 35169188, 2022). "It is reported that ALDH2 influences the removal of endogenous aldehydes generated by the ROS-mediated peroxidation such as 4-hydroxy-2-nonenal (4-HNE), and malondialdehyde (MDA), which are associated with high morbidity of cancer." (PMID 35477569, 2022).